CD163 (CD163 molecule)
Diseases named in the same sentence as CD163 in open-access papers (continued):
Sharing a sentence is not in itself a finding about the gene and the disease.
cancer (continued). "In our previous studies, tissues adjacent to early- and late-stage dysplasia, which in >90% of cases precede CRC tumors, were already found to show significantly increased levels of Rep+CD68+CD163+ MPs when compared to mucosal tissues of cancer-free individuals." (PMID 40136704, 2025). "The integration of multimarker panels (MCT, CD163, CD300a, CK18) could improve diagnostic accuracy by distinguishing between benign proliferations with active stroma and low-differentiation carcinomas." (PMID 41155492, 2025). "Interestingly, there was an inverse association between infiltration by CD163 + macrophages and TCF1 expression by cancer cells in luminal A, TNBC and HER2 + tumors." (PMID 38349444, 2024). "In addition, the observed inverse association between infiltrating CD163 + cells and TCF1 expression by cancer cells needs to be further investigated." (PMID 38349444, 2024). "Accumulated evidence suggests that a higher CD163+ TAMs count indicates poor prognosis and high metastatic potential in various cancers; however, how CD163 works in the protumoral activation of TAMs remains unclear." (PMID 38189834, 2024). "The drastic decrease in infiltrating M1 macrophages accompanying the increase in CD163/FKBP51s PB-TAMs raises the hypothesis of the relocation of cancer stem cells to other brain areas." (PMID 38651817, 2024). "Similarly, the non-cancer part of the peritoneal tissue was investigated as a basal count of CD163+ macrophages." (PMID 38745748, 2024). "The ectopic expression of CD163 on cancer cells due to cell fusion has been experimentally validated, has been reported in several cancer types and seems like a common and valid mechanism that needs to be considered in the design of anti-cancer immunotherapeutic approaches." (PMID 39451197, 2024). "Additionally, it has the potential to serve as a therapeutic intervention for various malignant tumor types that contain CD163+ TAMs." (PMID 39123373, 2024). "At the same time, it may provide a therapeutic intervention that could be utilized in different types of malignant tumors where CD163+ TAMs are present." (PMID 37082492, 2023). "In agreement, Goh and Ladiges observed in rodents that running on the treadmill increases the expression of anti-inflammatory markers (CD163) due to reduced inflammation related to the pre-development of cancer and by the decrease of the expression of M1-like markers (CD11c and TLR4)." (PMID 37179836, 2023). "However, a positive correlation was observed between the expression of IL-7R in ESCC cancer nests and the infiltration density of CD163- or CD204-positive cells, i.e., TAMs." (PMID 36672342, 2023). "Further, ~70% CD163+TIM4+ RTMs in malignant ascites were contributed by embryonic precursors." (PMID 37488416, 2023). "Although detailed mechanisms for this phenomenon that CD163 stained positively in cancer cells have been uncovered, soluble CD163 was suggested to be accumulated in cancer cells via unknown receptors." (PMID 37190178, 2023). "Interestingly, the expression of CD163 is not only restricted to TAMs but may also be associated with cell fusion where the fusion of cancer cells and TAMs can increase metastatic potential with migratory leukocytes in cancer patients and plays a role in cancer progression." (PMID 37397243, 2023). "However, the published evidence has largely centered on pathologists’ visual enumeration of CD163+ TAMs with limited capability to objectively capture prognostic value embedded in the spatial relationship between of CD163+ TAMs and cancer cells." (PMID 35053472, 2022). "Therefore, specific biomarkers on TAM, such as CD163, can be highly clinically relevant to evaluate the response to the treatment of cancer." (PMID 36551651, 2022). "We found a lot of CD163 positive cells in UTUC cancer and normal samples." (PMID 35464411, 2022).
cancer (continued). "Cancer diagnostic TAM markers, CD68, CD204, CD206, and CD163, are expressed on lung tissue AM; however, the poor MAFB expression on AM might significantly impact the assessment of cancer progression using TAM as an indicator." (PMID 36077342, 2022). "The SNV frequency of CD161 was 7% at the cancer level, lower than that of CD163 and CD8." (PMID 36660546, 2022). "Furthermore, the relationship between CD8, CD68, and CD163 in these cancers was verified by multiplex immunofluorescence staining." (PMID 36389798, 2022). "In addition, we quantified multiple combinations of cells positive for CD68, CD163, PD-L1, and CK in the stromal area, and compared the cell counts of sTAM subpopulations among the three cancer subtypes." (PMID 36362023, 2022). "The reported another receptor, CD163, which appeared on the macrophages and monocytes which could promote cell proliferation, was also observed with poor survival in cancer." (PMID 35707713, 2022). "In addition, the number of M2 macrophage markers-CD163 positive cells in most pan-cancer samples was significantly higher than that in para-cancerous tissues, suggesting the potential role of PDIA5 in the recruitment of M2 macrophage in the TME." (PMID 36003400, 2022). "However, CD163 was negatively (e and f), moderately (g and h), and strongly (i and j) expressed in the cytoplasm of the cancer cells." (PMID 36551651, 2022). "In addition, a positive correlation between the infiltration of CD163-positive macrophages into cancer and PD-L1 expression in cancer has been reported from observing tissues of various cancer patients." (PMID 36497144, 2022). "Furthermore, HCMV+ IBC cancer tissues are characterized by significantly high infiltration of CD163+ and MAC387+ TAMs in comparison with HCMV- IBC cancer tissues." (PMID 35847899, 2022). "However, the confidence intervals of this hazard ratio largely overlap with similarly adjusted hazard ratios for the dichotomized median cancer-to-CD163+ NND or the average number of adjacent CD163+ TAMs." (PMID 35053472, 2022). "We analyzed the following stromal markers that reflect different stromal cell populations: CD8 (cytotoxic T cells), CD163 (cancer-associated macrophages), fibroblast activation protein (FAP, for cancer-associated fibroblasts), and alpha-smooth muscle actin (SMA, for smooth muscle cells)." (PMID 36874403, 2022). "Thus, for the secondary analysis, we considered combining the strongest count-based predictor (the number of communicating CD163+ TAMs) with the median cancer-to-CD163+ NND." (PMID 35053472, 2022). "Next, we compared the different UICC stages of the corresponding invasive BTC tissues and observed no significant alterations except for a trend towards higher CD163+ macrophage density advanced stage carcinoma (UICC 3–4) compared to the precancerous stage (UICC 0; P = 0.038)." (PMID 36068277, 2022). "This may be because CD163+ TAM promotes cancer infiltration, while TIL causes an immune response to the cancer, affecting prognosis." (PMID 34089486, 2021). "A higher CD163+ macrophage count or an increase in M2/M1 Ratio in a variety of cancers indicates a poor prognosis or metastasis, although it remains unclear how CD163 works in the protumoral activation of TAMs." (PMID 33765961, 2021). "Controversies still exist regarding role of CD163 in cancer progression." (PMID 33906302, 2021). "Heterogeneity of macrophage phenotypes is observed among TAMs in various malignant tumors, but CD163+ TAMs may be the main population." (PMID 33765961, 2021). "We found higher median proportions of CD163-positive cells in the cancer group in CD14+16+ (98.08(86.40–100.00)%) and CD14low16+ (99.08(83.47–99.99)%) subsets compared to healthy women: 86.96(77.33–93.02)% for CD14+16+ (p = 0.049) and 60.00 (41.06–91.3)% for CD14low16+ (p = 0.004) cells." (PMID 35237501, 2021).
cancer (continued). "High carcinoma CSF-1R correlated with grade 3 tumors >2 cm, hormone receptor negativity, high Ki67, immune checkpoint biomarkers, and macrophages expressing CSF-1R and CD163." (PMID 34830923, 2021). "Previous studies indicated that CD163+TAM infiltration has a poor prognosis in many cancers." (PMID 32908942, 2020). "So far, only immunoliposomes targeting CD163 have been investigated in animal models of cancers." (PMID 32752088, 2020). "CD163 expression on TAMs correlates with poor prognosis in a number of human malignant tumors." (PMID 32752088, 2020). "Additionally, M1/M2 marker expression profiles of CD163+EPOR+ TAMs suggested a distinctive effect in supporting cancer progression." (PMID 32908942, 2020). "The inflamed phenotype presented with infiltration of many immune cells and increased intensity of CD8+T cells, infiltration of CD4+T cells, B cells (CD20+), and histocytes (CD163+) in the cancer cell nest, determined by immunohistochemistry, when compared with non-inflamed immune-activated RVT." (PMID 33299121, 2020). "Importantly we found a correlation between the intensity of MUC1-ST staining of the cancer cells and CD163+ macrophages in the stroma around the nests of cancer cells." (PMID 33149188, 2020). "Consistently, the polarized THP-1 cells revealed the induced amounts of M1 marker (iNOS and CD80) and the reduced amounts of M2 marker (CD163 and Arginase-1) while reacting with the cancer cells those were pretreated with Oligo-Fucoidan or in combination with cisplatin." (PMID 32059469, 2020). "In contrast, poor OS correlated with high expression of CD68 in ER− cases, while high expression of CD163 was associated with improved OS in ER− cases but not in ER+ cancers." (PMID 33194645, 2020). "Therefore, inhibition of TAM polarization to a CD163-positive M2 phenotype is a probable therapeutic strategy for cancer." (PMID 32256354, 2020). "While CD163-expressing macrophages are known to suppress inflammation in contexts such as cancer, they may potentially encourage fibrosis in HS." (PMID 32841223, 2020). "In addition, the M2-like polarization revealed by CD163 expression was induced when THP-1 cells were cocultured with the IL-6-treated cancer cells but was inhibited when THP-1 cells were cocultured with tocilizumab-treated cancer cells." (PMID 30885232, 2019). "Group A cancers had significantly higher numbers of infiltrating CD3+T-cells, CD4+T-cells, CD8+T-cells and CD20+B-cells compared to Groups B and C and Groups A and B cancers had significantly higher numbers of infiltrating CD163+ macrophages compared to Group C." (PMID 31431617, 2019). "Furthermore, both CD163 and CXCL5 are highly associated with inflammatory infiltrates, which are frequently detected in the lumen of malignant prostate glands.A relationship between the TWEAK/Fn14 axis and CD163 was also found in urine." (PMID 31500625, 2019). "Additionally, CD163-positive Mφs were highly accumulated in foci of RA and cancer patients; however, their implication for the pathogenesis has yet to be remained." (PMID 29559970, 2018). "Similar to cancer cell lines, but to a lesser extent, live mf significantly upregulated the cell surface expression of each of these markers (p = 0.001) with the exception of CD163." (PMID 29668679, 2018). "In vitro data suggest that cancer cells expressing CD163 acquire radioresistance." (PMID 29725763, 2018). "High expression of MMP-9 in the CD68+/CD163+ TAMs was associated with worse OS in ER+ tumors (P <0.001) but not in ER− cancers." (PMID 30558648, 2018). "Thus, CD163 staining is expected to reflect the status of macrophage infiltration into tumors and predict poor prognosis in cancer patients." (PMID 29323162, 2018). "In this study, we found that cancer cells could induce an M2-like macrophage characterized by up-regulation of CD163 and Arg1, and down-regulation of IL-1b and IL-6 through Nrf2 activation." (PMID 30180849, 2018).
cancer (continued). "CD163 in cancer cells is involved in the progression and can be upregulated by STAT3." (PMID 29152078, 2017). "Both antibodies against monocytes/macrophage markers, F4/80 and CD163 do not stained CAFs populations, ruling out the presence of macrophages and identified the isolated cells as cancer-associated fibroblasts (CAFs)." (PMID 28178651, 2017). "High CD163 level in cancer cells is a potential marker of poor prognosis." (PMID 29152078, 2017). "Interestingly, the survival time of patients with high expression of CD163 in cancer cells was significantly reduced too." (PMID 29152078, 2017). "As expected, overexpressing STAT3 in cancer cells was able to elevate the expression of CD163." (PMID 29152078, 2017). "This study replenishes the knowledge of CD163, and further prospective research may allow us to validate whether CD163 is a novel therapeutic target for cancer." (PMID 29152078, 2017). "Importantly, the expression of CD163 in cancer cells had a significant relationship with E-cadherin and vimentin." (PMID 26769084, 2016). "In addition, CD68, CD163 and HO-1 expression was also observed on AMs in lung tissue adjacent to the cancer margin." (PMID 26900851, 2016). "In addition to expression on monocyte-derived cells, expression of CD163 and other macrophages antigens on cancer cells have been described." (PMID 26111002, 2015). "Further, the expression of CD163 in cancer cells could be explained by other biological processes like abnormal phenotypic expression in cancer cells and paracrine cellular interaction between cancer cells and macrophages." (PMID 26585897, 2015). "Relation between CD163 expression in cancer tissues and MDSC% in PBMC from ECA patients." (PMID 25144454, 2014). "Moreover, the increased ratio of MDSC in PBMC from ECA patients was closely related to the expression of CD163 in cancer tissues." (PMID 25144454, 2014). "Our data indicate that the increased Th2 cytokines are associated with MDSCs and M2 macrophages polarization, and foster the infiltration of CD163+M2 macrophages in cancer tissues, which promote the formation of immunosuppressive microenvironment in ECA patients." (PMID 25144454, 2014). "Notably, the increased ratio of MDSCs in PBMCs from ECA patients was closely related to the expression of CD163 in cancer tissues." (PMID 25144454, 2014). "Based on in vitro studies, it has been suggested that CD163 may be a M2 marker and studies of human tissues, e.g., in cancer research, have considered CD163+ cells identified by immunohistochemistry as M2 macrophages." (PMID 24260507, 2013). "CD163-positive cancers had more severe histological aberrations due to genomic instability." (PMID 22353646, 2012). "Interestingly, there is evidence of a correlation between the presence of CD163-expressing macrophages and more aggressive growth across various types of cancer suggesting that the presence of higher numbers of CD163 immunoreactive macrophages is indicative of a poor prognosis." (PMID 40191733, 2025). "The three cell components within the lung metastatic niche, including CD163+ macrophages, neutrophils, and endothelial cells, expressed elevated levels of ApoE, leading to the secretion of various protumorigenic molecules that promote cancer cell growth in the lung." (PMID 39695088, 2024). "Thus, the CD8/CD163 ratio can potentially impact the decision-making process regarding mTNBC therapies, specifically harnessing the full capability of the immune system in combating cancer." (PMID 38308298, 2024). "Interestingly, many CD163+ TAMs were found to proliferate within the TME of various cancers." (PMID 38903497, 2024). "Consistently, novel findings revealed a cancer-protective function of sympathetic nerves during the development and progression in the murine model of pancreatic cancer mediated by the local suppression of cancer-promoting and immunosuppressive CD163+ macrophages in the TME." (PMID 39906323, 2024).
cancer (continued). "In contrast, markers associated with suppressive populations of myeloid cells (CD163, B7-H3, VISTA) and T cells (CD4, LAG3, Tim-3) were expressed at a higher level in CD45+ segments in the ‘surrounding stromal leukocyte’ regions (cf. ‘immune-rich cancer cell islet’ regions)." (PMID 37046826, 2023). "Higher levels of CD163, CD14, Fibronectin, B7-H3, LAG3, Tim-3, PD-L1, VISTA, CD25, and CD44 associated with fibroblasts, myeloid-derived cells, T cells, and NK cells were found in the ‘surrounding stromal leukocytes’ cf. ‘immune-rich cancer cell islet’ regions." (PMID 37046826, 2023). "Classically activated macrophages expressing CD68 (M1) are correlated to antigen presentation and inflammatory response, whereas alternatively activated macrophages expressing CD163 (M2) may be involved in cancer growth, angiogenesis, metastasis and therapy resistance." (PMID 36982316, 2023). "Therefore, the blockade of TIM-3 on CD14+CD68+CD163+ macrophages might improve cancer immunosuppression." (PMID 36293034, 2022). "In our study, although the overall number of cancer cases was enough to obtain good-quality results, more data and cases about CD163 are still needed because of unequal distribution after grouping based on age and sex, which may explain the lack of differences in the survival analysis." (PMID 36551651, 2022). "As described in the Methods section, we also computed alternative spatial proximity metrics of the average number of CD163+ TAMs that are (i) directly adjacent to (within 12 μm distance or (ii) within paracrine cyto/chemokine communicating distance (within 250 μm distance) of each cancer cell." (PMID 35053472, 2022). "Moreover, the immune system is found to promote the formation of mechanical microenvironment, especially the macrophages (CD68 and CD163 positive) infiltrated in cancer can secrete TGF-β, which mediates the production of collagen and activates LOX, leading to collagen crosslinking." (PMID 35803912, 2022). "For the comparison of cancer tissues and adjacent tissues, CD40high is a common feature of CD163+ mono-macrophage subset, suggesting that this molecule may play an important role in biological functions of the CD163+ mono-macrophage subset." (PMID 34803459, 2021). "In addition, a significantly positive correlation (p < 0.001) is also observed between CSF-1R+ carcinoma cells and macrophages expressing CSF-1R and CD163, supporting the plausible existence of a CSF-1/CSF-1R paracrine signaling mechanism as has been suggested in the preclinical studies." (PMID 34830923, 2021). "It was reported that poor prognosis is linked to increased levels of CD163 (TAM marker with M2 phenotype), CSF-1 (colony-stimulating factor-1), major regulator of macrophage lineage, and Arginase-1 (Arg-1) – markers of TAM’s activity – in several cancers including the HPV-related ones." (PMID 29976244, 2018). "Strikingly, CD163 staining also could be observed in some cancer cells." (PMID 29152078, 2017). "That stroma cells in cancer tissues may interfere the results of CD163 in cancer cells." (PMID 29152078, 2017). "CD163 may also prove to be a useful cancer cell fusion biomarker in clinical contexts." (PMID 27136533, 2016). "CD163 (Gene ID#9332) is a member of the scavenger receptor cysteine-rich superfamily, which may reflect proinflammatory cytokine production, and there are various reports linking its expression with poor prognosis in various cancers." (PMID 26267609, 2015). "Myeloid markers (e.g., CD163) were predominantly expressed in benign adrenal cortical adenomas, whereas lymphoid markers (e.g., CD8) were elevated in malignant tumors." (PMID 40190189, 2025). "When cultured, they expressed specific M2 polarization markers (CD163, CD204, CD206), providing evidence of M2 macrophages role as fusogenic partners of different types of cancer cells both in vitro and in vivo, generating THCs." (PMID 39967663, 2025).